ALMS1 (ALMS1 centrosome and basal body associated protein)
Diseases named in the same sentence as ALMS1 in open-access papers (continued):
Sharing a sentence is not in itself a finding about the gene and the disease.
Usher syndrome (3 papers, 2018 to 2024). A syndromic diseae characterized by the association of sensorineural deafness (usually congenital) with retinitis pigmentosa and progressive vision loss. "This strategy would still not suffice for treatment of IRDs such as Usher syndrome type 1D or Alström syndrome type I (ALMS) due to mutations in CDH23 or ALMS1, respectively." (PMID 29292161, 2018).
dyslipidaemia (2 papers, 2018 to 2024). "Pdgfrα-cre driven KO of Alms1 (MSC KO) recapitulated insulin resistance, fatty liver, and dyslipidaemia in both sexes." (PMID 38583571, 2024).
retinitis pigmentosa (2 papers, 2015 to 2018). Retinitis pigmentosa (RP) is an inherited retinal dystrophy leading to progressive loss of the photoreceptors and retinal pigment epithelium and resulting in blindness usually after several decades. "We then tested whether subretinal administration of triple AAV2/8 vectors results in expression of CDH23 and ALMS1, which are both mutated in syndromic forms of retinitis pigmentosa." (PMID 29292161, 2018).
schizophrenia (2 papers, 2018). A major psychotic disorder characterized by abnormalities in the perception or expression of reality. "Intriguingly, Sherlock analysis also suggested that ALMS1 is a causal gene for schizophrenia." (PMID 29540662, 2018). "These consistent results strongly suggest that ALMS1 may represent a promising causal gene for schizophrenia." (PMID 29540662, 2018). "Sherlock integrative analysis shows that ALMS1, GLT8D1, and CSNK2B are schizophrenia risk genes, which are validated using independent brain expression quantitative trait loci (eQTL) data and integrative analysis method (SMR)." (PMID 29483533, 2018). "These convergent lines of evidence suggest that the ALMS1, CSNK2B, and GLT8D1 genes may be involved in pathophysiology of schizophrenia." (PMID 29483533, 2018).
scoliosis (2 papers, 2025). A congenital or acquired spinal deformity characterized by lateral curvature of the spine. "The characteristics of the scoliosis curves in our subject case were consistent with idiopathic rapid curve progression, likely accelerated by 18 years of higher phenotypic aging in individuals with ALMS1 mutation, requires careful monitoring." (PMID 40676683, 2025). "ALMS1 regulates ciliary function and structure, mutations in this gene could contribute to the development of scoliosis in ALSM." (PMID 40676683, 2025).
steatosis (2 papers, 2021 to 2024). Increased lipid within the cytoplasm of cells. "We can assume that the initial presence of steatosis was replaced very early by fibrosis, partly by common mechanisms of NAFLD progression and partly by the specific role of dysfunctional ALMS1 protein in liver cells." (PMID 33924909, 2021). "The hepatic steatosis in female Alms1 MSC KO is notable given intact hepatocyte Alms1 expression, confirming that fatty liver in AS does not require hepatic Alms1 deficiency." (PMID 38583571, 2024). "Thus, the classical NAFLD progression from steatosis to fibrosis does not completely explain the liver disease in ALMS, and we could suggest the involvement of ALMS1 deficiency in the liver disease of patients with ALMS." (PMID 33924909, 2021).
acute myocardial infarction (1 paper, 2024). Necrosis of the myocardium, as a result of interruption of the blood supply to the area. "For instance, ALMS1 is considered a biomarker for the diagnosis and prognosis of acute myocardial infarction (AMI), with specific variants, such as G/A variant (rs674804) and glutamic acid repeat polymorphism, being markers for early-onset myocardial infarction." (PMID 39126056, 2024).
cardiac hypertrophy (1 paper, 2024). "In Sphynx cats, it has been revealed that the mutation of the ALMS1 gene is associated with the development of cardiac hypertrophy." (PMID 38970022, 2024).
congenital stationary night blindness (1 paper, 2021). "ALMS1 mutations cause autosomal recessive Alström syndrome whereas TRPM1 mutations are associated with recessive congenital stationary night blindness." (PMID 34485303, 2021).
coronary atherosclerosis (1 paper, 2009). Atherosclerosis of the coronary vasculature. "Confirmation of ALMS1 gene mutations in a patient is a strong indication for cardiac magnetic resonance imaging to be performed and for treatment of risk factors for coronary atherosclerosis." (PMID 19515241, 2009).
fatty liver (1 paper, 2024). "ALMS1 is globally expressed, but the metabolic profile of AS is reminiscent of the dyslipidemic severe IR and fatty liver of lipodystrophy." (PMID 38583571, 2024). "We predicted that restricting Alms1 KO to Pdgfra-expressing cells would abolish hyperphagia but induce severe IR, and fatty liver disease, despite intact hepatocyte Alms1 expression." (PMID 38583571, 2024).
head and neck squamous cell carcinoma (1 paper, 2021). A squamous cell carcinoma that arises from any of the following anatomic sites: lip and oral cavity, nasal cavity, paranasal sinuses, pharynx, larynx, and salivary glands. "Previous studies found that ALMS1 was the lncRNA that targets the most mRNAs and proteins in head and neck squamous cell carcinoma (HNSCC), which related to the progression and prognosis of cancers." (PMID 34745388, 2021).
heart defects (1 paper, 2021). "Next, we confirmed ALMS1 expression in heart tissue samples using our previously reported RNA-seq data of congenital heart defects samples obtained from infants with structural heart defects." (PMID 34387706, 2021).
Hodgkins lymphoma (1 paper, 2017). A heterogeneous group of malignant lymphoid neoplasms of B-cell origin characterized histologically by the presence of Hodgkin and Reed-Sternberg (HRS) cells in the vast majority of cases. "DNA microarray analysis suggested that ALMS1 might be differentially expressed between Hodgkin lymphoma (HL) cells and normal tissues." (PMID 28135309, 2017).
hyperopia (1 paper, 2025). A refractive error in which rays of light entering the eye parallel to the optic axis are brought to a focus behind the retina, as a result of the eyeball being too short from front to back. "Hyperopia is common in some IRDs including AD BEST1-retinopathy, RS1 and some LCA genotypes (in the current cohort: AIPL1, ALMS1, CEP290, CRB1, CRX, TULP1)." (PMID 41465105, 2025).
Hypoglycemia (1 paper, 2024). A decreased concentration of glucose in the blood. "Male global Alms1 KO mice showed reduced insulin-induced hypoglycemia, while MSC KO in males produced a trend towards reduction." (PMID 38583571, 2024).
insulinoma (1 paper, 2022). "Interestingly, transient knockdown of ALMS1 (siRNA-Alms1) in the β-TC-6 mouse insulinoma cell line resulted in constitutive insulin secretion independently of glucose concentrations." (PMID 35832432, 2022).
liver disease (1 paper, 2021). "Thus, better knowledge of ALMS1 protein function in liver fibrogenesis could expand the pathways involved in NAFLD/NASH hepatic disease present also in more common metabolic diseases." (PMID 33924909, 2021).
liver dysfunction (1 paper, 2019). "The patient's heterozygous mutation in ALMS1 may have been a contributing factor, since liver dysfunction is a component of autosomal recessive Alstrom Syndrome." (PMID 30977266, 2019).
migraine with aura (1 paper, 2025). A migraine disorder characterized by episodes that are preceded by focal neurological symptoms. "At the brain‐tissue level, we further validated hub gene associations: in migraine, SERPINC1, ZKSCAN8P1, C12orf76, and PAM were significant across brain regions; in migraine with aura, SERPINC1, ALMS1, ZKSCAN8P1, PAM, and NCF2 were significant." (PMID 41261954, 2025). "For migraine with aura, MICA (p = 2.82×10−7), GPATCH4 (p = 2.39×10−5), BBS4 (p = 7.64×10−4), ALMS1 (p = 8.40×10−4), and CCDC180 (p = 3.38×10−3) were the five most significant ones." (PMID 41261954, 2025). "SMR and INTACT confirmed the validity of BLM, C12orf76, GPATCH4, PAM, SERPINC1 for migraine, and ALMS1, GPATCH4, NCF2, SLC12A1, ZKSCAN8P1 for migraine with aura." (PMID 41261954, 2025). "For migraine with aura, SERPINC1, ALMS1, ZKSCAN8P1, PAM, and NCF2 were significant (p < 0.05); SERPINC1 was significant in nine regions, with the most pronounced association in the Nucleus accumbens (basal ganglia) (p = 0.014)." (PMID 41261954, 2025). "The results of the SMR, colocalization, and INTACT sensitivity analyses provided further validation of BLM, C12orf76, GPATCH4, PAM, SERPINC1 as contraindicated drugs’ target genes for migraine, and ALMS1, GPATCH4, NCF2, SLC12A1, ZKSCAN8P1 for migraine with aura." (PMID 41261954, 2025).
multiple myeloma (1 paper, 2019). "Encoded by gene ALMS1, such peptide loading protein has been only identified in multiple myeloma but not in other tumor subtypes and normal controls." (PMID 31850330, 2019).
non-alcoholic steatohepatitis (1 paper, 2022). "Indeed, due to their deficiency for Alms1, a protein essential for primary cilium function, they are hyperphagic and prone to develop obesity and systemic IR together with progressive MAFLD from steatosis to fibrosing non-alcoholic steatohepatitis (NASH)." (PMID 35888749, 2022).
prostate carcinoma (1 paper, 2024). A carcinoma that arises from epithelial cells of the prostate gland. "This group of four genes would not have been detected using a single signature as ALMS1 is mutated in prostate cancer while the other three are over-expressed." (PMID 38983753, 2024).
cancer (6 papers, 2017 to 2024). A tumor composed of atypical neoplastic, often pleomorphic cells that invade other tissues. "Therefore, such peptide may also be potential biomarkers for immunosignature recognition-based cancer diagnosis and prognosis in real-time because of its potential relationship with ALMS1, distinguishing unique cancer subtypes." (PMID 31850330, 2019). "In the second dataset all the CGC genes (5/507) were classified as oncogenes by OncoScore and 4 (4/302) out of 5 nCan genes (ALMS1, DCAF17, GPD1L and WFS1) were classified as ‘non-cancer’ at the final time point, as expected." (PMID 28387367, 2017). "Further, five genes, ALMS1, TRAPPC9, CEP128, OR10T2, and CPVL, are among the SCLC genes but not in any of the common cancer gene lists, yet these genes were mutated in M9." (PMID 29050228, 2017).
genetic disorder (5 papers, 2017 to 2026). "AS is a rare genetic disorder caused by mutations in the ALMS1 gene." (PMID 38022732, 2023).
metabolic disorders (4 papers, 2009 to 2025). "The present study focused on the effects of Alms1 disruption on adipose tissue, in a mouse model recapitulating the metabolic disorders observed in ALMS patients." (PMID 25299671, 2014).
heart disease (3 papers, 2023 to 2024). "Several measures are worthy of consideration in future to increase the value of the Alms1 KO mouse as a cardiac disease model." (PMID 38756069, 2024). "Understanding the cardiac phenotype of Alms1 KO mice may be clinically relevant to patients with AS and may also provide insights into common cardiac disease." (PMID 38756069, 2024). "ALMS1 p.G3376R is a Sphynx-specific mutation that has been reported in a few carriers of over 200 non-Sphynx cats without known heart disease." (PMID 37071642, 2023).
infection (2 papers, 2018 to 2022). The state of being infected such as from the introduction of a foreign agent such as serum, vaccine, antigenic substance or organism. "First, we observed that the real-time qPCR amplification using primers D (located at the 3′ end of vector 2) and E (located at the 5′ of vector 3) following infection with AAV 2 + 3 is significantly lower than the one obtained when AAV 1 + 2 + 3 are used (2% for CDH23 and 20% for ALMS1)." (PMID 29292161, 2018).
neurodevelopmental disorder (1 paper, 2018). A behavioral and cognitive disorder with onset during the developmental period that involves impaired or aberrant development of intellectual, motor, or social functions. "Mutation or disruption of ALMS1 and CSNK2B lead to severe neurodevelopmental disorder, indicating these two genes are essential for neurodevelopment." (PMID 29483533, 2018).
skeletal dysplasia (1 paper, 2021). Any Mendelian diseases that affects growth and development of the skeleton. "Almost 20 ciliary genes are associated with skeletal dysplasias, and biallelic variants in other ciliary genes (ALMS1, IFT172, and KIAA0753) have been discovered in individuals with growth hormone deficiency." (PMID 34194391, 2021).
ALMS1 also shares sentences with these, for which no sentence is quoted: acanthosis nigricans (2 papers); Alport syndrome (2); Blindness (2); hyperandrogenemia (2); Infertility (2); neurosensorial deafness (2); non-alcoholic fatty liver disease (2); tumor (2); -dependent (1); alopecia (1); anovulation (1); Arts syndrome (1); atherosclerosis (1); autosomal recessive disease (1); biotinidase deficiency (1); carnitine deficiency (1); Clouston syndrome (1); dental caries (1); dentinogenesis imperfecta (1); developmental delay (1); diabetic ketoacidosis (1); DiGeorge syndrome (1); dyslexia (1); elliptocytosis (1); endocardial fibroelastosis (1); erythrokeratodermia variabilis (1); familial dilated cardiomyopathy (1); familial hypertrophic cardiomyopathy (1); fibrosis (1); hereditary hemorrhagic telangiectasia (1).
A further 35 diseases each share a sentence with ALMS1 in 1 paper.